SCO2 (synthesis of cytochrome C oxidase 2)
Description:
Copper metallochaperone essential for the synthesis and maturation of cytochrome c oxidase subunit II (MT-CO2/COX2); together with SCO1, facilitates the incorporation of copper into the Cu(A) site of MT-CO2/COX2. Could also act as a thiol-disulfide oxidoreductase to regulate the redox state of the cysteines in SCO1 during maturation of MT-CO2/COX2.
Synonyms: SCO1L; CEMCOX1; ECGF1; Gliostatin; MC4DN2; MYP6; PD-ECGF; TP; TdRPase
Tractability: Small molecule: it has a high-quality binding pocket. Antibody: UniProt predicts a signal peptide or a membrane-spanning region. PROTAC: ubiquitination databases record sites on it; its protein half-life has been measured.
Safety:
Unwanted effects reported when the protein is acted on. In parentheses: how it was acted on, where the effect was seen, and who reports it.
drug toxicity (source: ClinPGx)
drug toxicity and may require dose modification (source: ClinPGx)
Gene: Protein-coding gene on chromosome 22 (50,523,564 to 50,526,461, reverse strand). Ensembl gene ENSG00000284194.
Subcellular location: Mitochondrion inner membrane
Subcellular location (Human Protein Atlas): Mitochondria
Pathways (Reactome):
Metabolism: Complex IV assembly
Gene Ontology:
Molecular function: protein binding; protein-disulfide reductase activity; copper ion binding; copper chaperone activity
Biological process: eye development; mitochondrial respiratory chain complex IV assembly; intracellular copper ion homeostasis; respiratory chain complex IV assembly
Cellular component: mitochondrial inner membrane; mitochondrion; myofibril
Genetic constraint (gnomAD): Loss-of-function variants: 5 observed, 5.34 expected, observed/expected ratio (o/e) 0.94, 90% interval 0.48 to 1.76. That is too few expected variants to judge how well the gene tolerates losing a copy. Missense variants: 429 observed, 354.84 expected, observed/expected ratio (o/e) 1.21, 90% interval 1.12 to 1.31. Synonymous variants: 195 observed, 151.1 expected, observed/expected ratio (o/e) 1.29, 90% interval 1.15 to 1.45.
Gene-disease validity (ClinGen):
ClinGen rates the evidence that SCO2 causes each of these diseases.
Leigh syndrome (autosomal recessive): Definitive. A progressive neurological disease defined by specific neuropathological features associating brainstem and basal ganglia lesions.
mitochondrial disease (autosomal recessive): Definitive.
Charcot-Marie-Tooth disease (autosomal recessive): Moderate. An inherited degenerative disorder involving the peripheral nerves.
Homologues: Orthologues: chimpanzee SCO2 (98% identical), rabbit SCO2 (81% identical), dog SCO2 (81% identical), pig SCO2 (80% identical), mouse Sco2 (77% identical), guinea pig SCO2 (77% identical), zebrafish sco2 (53% identical), tropical clawed frog sco2 (50% identical). Paralogues in human: SCO1 (37% identical).